LINC01365 (long independently transcribed non-coding RNA 1365)
Gene: Long non-coding RNA gene on chromosome 4 (119,799,089 to 119,804,554, reverse strand). Ensembl gene ENSG00000250772.
Diseases named in the same sentence as LINC01365 in open-access papers:
LINC01365 is named in the same sentence as 2 diseases in open-access papers, as found by Europe PMC text mining. Sharing a sentence is not in itself a finding about the gene and the disease. The quoted sentences say what the papers report.
cancer (1 paper, 2019). A tumor composed of atypical neoplastic, often pleomorphic cells that invade other tissues. "When relaxing the q-value cutoff to 0.1, LINC01365, ZNF503-AS1 and LINC00689 were identified as riboSNitch-enriched, among which ZNF503-AS1 and LINC00689 were cancer-specific." (PMID 31160636, 2019).
LINC01365 also shares sentences with these, for which no sentence is quoted: Alzheimer disease (1 paper).